ARG1 (arginase 1)
Diseases named in the same sentence as ARG1 in open-access papers (continued):
Sharing a sentence is not in itself a finding about the gene and the disease.
Senile plaques (1 paper, 2022). Senile plaques are extracellular deposits of amyloid in the gray matter of the brain. "One with high expression levels of IL-1β, TNF-α and IL-12A typical of a pro-inflammatory phenotype related with oligomeric Aβ, the other located near senile plaques with upregulation of IL-1ra, Arginase 1 and FIZZ, is characteristic of a reparative phenotype." (PMID 35011699, 2022).
septic shock (1 paper, 2024). Shock caused by infection; frequently caused by gram negative bacteria, although some cases have been caused by other bacteria, viruses, fungi, and protozoa; characterized by fever, chills, tachycardia, tachypnea, and hypotension. "Quantitative Reverse Transcription Polymerase Chain Reaction validation was conducted for MMP8, MMP9, ARG1, HP, and CD163 across healthy controls, SIRS, and septic shock patient groups." (PMID 39560539, 2024).
Sjögren syndrome (1 paper, 2022). "Plasma concentration of Arg-1 was also negatively correlated to the frequency of Th17 cells in RA and disease activity in Sjögren syndrome." (PMID 35847216, 2022).
subarachnoid haemorrhage (1 paper, 2025). "Arg1 has been identified in MSC-EVs, promoting microglial M2 polarisation after subarachnoid haemorrhage in rats." (PMID 41488750, 2025).
T cell deficiency (1 paper, 2022). "In contrast to T cell deficiency, the recurrent tumors were significantly enriched for markers of tumor-associated neutrophils (TANs; eg., CD177, ELANE), tumor-associated macrophages (TAMs; eg., MRC1, CD68), and immune suppressive myeloid cells (MDSCs; eg., ARG1, CXCR4)." (PMID 35919862, 2022).
teratoma (1 paper, 2014). A non-seminomatous germ cell tumor characterized by the presence of various tissues which correspond to the different germinal layers (endoderm, mesoderm, and ectoderm). "The distributions of angiopoietin (Ang) receptor (Tie)-2+ (Tie-2) cells and F4/80+/arginase-1+ macrophages were detected in the teratoma in vivo." (PMID 25071759, 2014). "ESC-educated macrophages produce high levels of arginase-1, Tie-2, and TNF-α, which participate in angiogenesis and contribute to teratoma progression." (PMID 25071759, 2014).
thrombotic microangiopathy (1 paper, 2024). The syndromes of microangiopathic hemolytic anemia, thrombocytopenia, and variable signs of organ impairment, due to platelet aggregation in the microcirculation. "In the in vitro model of thrombotic microangiopathy, bioactive arginase 1 was released and levels correlated to the degree of hemolysis." (PMID 38178089, 2024).
tongue cancer (1 paper, 2021). A malignant neoplasm affecting the tongue. "To explore this, we performed gene expression profiling on oral tongue cancer cells that had been transfected with ARG1 and compared this with untransfected controls." (PMID 34885177, 2021). "In general, the results show that ARG1 overexpression had an inhibitory effect on oral tongue cancer cell viability and proliferation." (PMID 34885177, 2021). "We showed that reprogramming arginase 1 (ARG1) expression in tongue cancer cells inhibits growth compared with controls." (PMID 34885177, 2021). "Firstly, we show that ARG1, the enzyme responsible for the catabolism of arginine, is not expressed by oral tongue cancer cells." (PMID 34885177, 2021). "Considering the lack of expression of ARG1, we next sought to determine whether oral tongue cancer cells had adapted to function and proliferate without relying on arginine catabolism." (PMID 34885177, 2021).
tongue tumors (1 paper, 2019). "Furthermore, we observed that supplementing α-PD-1 + α-CTLA-4 treatment with STING agonist administration into the flank tumors was associated with a decrease in the frequencies of CD4+Foxp3+ Treg as well as of MDSC expressing Arginase 1 in both flank and tongue tumors." (PMID 31533840, 2019).
trauma (1 paper, 2023). "An expansion in spleen resident MDSCs has also been reported in a murine model of neurological trauma, which was accompanied by a significant increase in arginase-1 (ARG-1) expression in CD11b+ monocytes." (PMID 37662933, 2023).
tuberculous pleurisy (1 paper, 2024). "The aim of the present study was to investigate the role of M2 Arg-1+ MФ in tuberculous pleurisy-assisted tumorigenicity in vitro and in vivo." (PMID 38720340, 2024).
ulcers (1 paper, 2022). "The authors found that, in nonhealing ulcers examined over a period of 6 weeks, the CD68+Arg1+ population was significantly reduced in comparison with that in healing ulcers." (PMID 35954275, 2022).
Ureteral obstruction (1 paper, 2021). Obstruction of the flow of urine through the ureter. "In a single-cell atlas of mouse model of unilateral ureteral obstruction (UUO), monocytes recruited to the kidney early after injury rapidly adopt a proinflammatory, profibrotic phenotype that expresses Arg1+ M2 macrophages." (PMID 35003086, 2021).
uterine tumors (1 paper, 2014). "In the current research, we have evaluated the expression of PD-L1, PD-L2, B7-H4, IDO, galectin-1 and galectin-3 in uterine tumors and documented the arginase-1 activity and MDSC infiltration in these tumors." (PMID 24658839, 2014). "The activity of arginase-1 in uterine tissue samples was determined, and we further provided evidence of MDSC infiltration in uterine tumor specimens by multi-parametric flow cytometry." (PMID 24658839, 2014). "In conclusion, we report the presence of the immune checkpoints PD-L1/PD-L2 and B7-H4 in uterine tumors as well as the presence of the immune inhibitory molecules IDO, arginase-1, galectin-1 and galectin-3 and the immunosuppressive MDSC." (PMID 24658839, 2014). "In an attempt to shed more light on the immunosuppressive environment in uterine tumors, we analyzed the presence of PD-L1, PD-L2, B7-H4, indoleamine 2,3-dioxygenase (IDO), galectin-1, galectin-3, arginase-1 activity and myeloid-derived suppressor cell (MDSC) infiltration." (PMID 24658839, 2014).
uveitis (1 paper, 2025). An inflammatory process affecting a part of or the entire uvea. "Among these, the Major Histocompatibility Complex (MHC) class II and the enzyme Arginase 1 (ARG1) were significantly enriched in RMG from uveitis-affected horses, whereas Mannose Receptor C-type 2 (MRC2) and its interactor Thrombospondin 1 (THBS1) were more abundant in healthy RMG." (PMID 40001591, 2025). "In other uveitis models, however, increased levels of ARG1 in RMG was evident." (PMID 40001591, 2025). "Next, we investigated the expression and precise distribution of ARG1 in healthy retinas (DIC) and retinas from uveitis cases (DIC)." (PMID 40001591, 2025).
ZIKV infection (1 paper, 2020). "We found reduced Arg-1 expression in microglia following ZIKV infection, suggesting to us that ZIKV may cause damage in the brain through inhibiting neuroprotective factors." (PMID 32843067, 2020).
tumor (1,479 papers, 2010 to 2026). "Increased ARG1 expression in epithelial ovarian cancer is associated with immune suppression and tumour growth, whereas ARG1 inhibition reduces ARG1‐mediated immune suppression and tumour progression." (PMID 41503514, 2026). "ARG1, primarily triggered by polymorphonuclear granulocytes (PMNs) in humans, is linked to the acceleration of tumour growth and enhanced immunosuppression." (PMID 41503514, 2026). "Tumor-associated neutrophils and MDSCs can release IL-10 or Arg-1, which also influence macrophages toward M2." (PMID 41597210, 2026). "Peripherally, the hormone reverses the arginase-1–dominant metabolism of tumour-associated macrophages, reinstating iNOS activity and nitric-oxide production that favour cytotoxic immunity over wound-healing fibrosis." (PMID 40791587, 2025). "Lactylation, for example, activates genes such as Arg1, which is a hallmark of the M2 macrophage phenotype implicated in immunosuppression and tumor growth." (PMID 39968078, 2025). "To further explore the immune dynamics associated with the NOS2/ARG1 axis and tumor behavior we analyzed the proportions of circulating immune cells." (PMID 41573553, 2025). "For instance in glioma tumors, arginine deprivation reduces ARG1 expression in tumor-associated macrophages/microglia and enhances their proinflammatory and phagocytic function." (PMID 39863828, 2025). "Tumor cells and immunosuppressive cells (e.g., tumor-associated macrophages (TAMs) and myeloid-derived suppressor cells (MDSCs)) express enzymes like arginase 1 (Arg-1) and indoleamine 2,3 dioxygenase (IDO1), depleting arginine and tryptophan in the TME." (PMID 40944200, 2025). "For instance, while arginine is mainly metabolized by ARG2 in tumor-associated T cells, it is metabolized by ARG1 in lung CD4+ T cells upon influenza infection." (PMID 39863828, 2025). "Simultaneously, lactate-induced histone lactylation further upregulates the expression of arginase 1 (Arg1), a key marker of M2-type macrophages (tumor-associated macrophages, TAMs)." (PMID 41007358, 2025). "The GBM microenvironment predominantly contains tumor-promoting Arginase 1 (Arg1)high, inducible nitric oxide synthase (iNOS)low tumor-associated microglia/macrophages (TAMs)." (PMID 41227348, 2025). "This means that high lactate levels can reprogram cells at the epigenetic level, for example, driving tumor-associated macrophages (TAMs) toward a pro-tumor M2 phenotype by inducing genes like ARG1 and VEGF that support tissue remodeling and immunosuppression." (PMID 40723880, 2025). "Since expansion of neutrophils and MDSCs also is associated with their infiltration into the tumor, we performed meta-analysis of ARG1 gene expression in tumor biopsies using the Kaplan-Meier plotter database." (PMID 40474277, 2025). "This is evidenced by the dose-dependent reduction in the serum levels of the IL-10 (M2-specific cytokines) and Arg-1 (hallmark marker for M2 macrophages) following L-K5 treatment, which correlated with inhibited tumor growth and reduced liver metastasis." (PMID 40943546, 2025). "Further analysis of immune‐infiltrating cells within the TME indicated that ARG1 expression was lower in tumor‐associated MDSCs from Ch25hf/fLyz2Cre(±) homozygous mice compared to those from Ch25hf/f homozygous mice." (PMID 41020041, 2025). "IL-19 blockade promoted T cell activation and reprogrammed tumor-associated macrophages toward weakened pro-tumoral phenotypes with reduced Arginase 1 expression." (PMID 40057744, 2025). "Additional histologic markers such as Glypican-3, Arginase-1, and HepPar-1 help refine diagnostic accuracy, particularly in poorly differentiated tumours." (PMID 41583252, 2025). "TANs can also secrete Arg1 to cause the degradation of arginine, thus inhibiting anti-tumor responses." (PMID 40131539, 2025).
tumor (continued). "Neutrophils, on the other hand, promote tumor occurrence through immunosuppression via mediators such as ROS, inducible nitric oxide synthase, and arginase 1, and are often associated with poor prognosis in patients." (PMID 39883700, 2025). "ARG1hi (Arginase 1) macrophages and cancer-associated fibroblasts (CAFs) were enriched at the tumor boundary furthest from the adjacent lung (distal tumor boundary)." (PMID 40705858, 2025). "Lactate secreted by tumor cells can promote tumor development by inducing M2-like polarization and Arginase-1(Arg-1) expression in tumor-associated macrophages (TAMs)." (PMID 40917754, 2025). "In parallel, monocytes and tumor-associated macrophages (TAMs) expressing markers such as Arg1, Spp1, and Il1b, are known to contribute immune suppression in PDAC and other malignancies." (PMID 40661354, 2025). "Differential gene expression analysis using FindMarkers on tumor-associated macrophages revealed significant downregulation of M2 polarization markers (Arg1, Tgfb1) post-BBR treatment." (PMID 41585886, 2025). "In GBM, tumor-associated endothelial cells induce HIF-2α-dependent upregulation of Arg1 expression through secretion of IL-6, thereby promoting M2 polarization of TAMs and facilitating cancer progression." (PMID 40453088, 2025). "Tumor cells upregulate ARG1 and iNOS to deplete extracellular L-arginine, causing T cell dysfunction and immune evasion." (PMID 41036604, 2025). "Arginine depletion in the TME resulting from high expression of Arg1 in other tumor cells causes inhibition of mTORC1 activity in T cells, resulting in a decrease in effector functions and an increase in memory phenotype." (PMID 39796781, 2025). "The CD66b neutrophil marker was positively correlated with the immunosuppressive protein Arg1, which is a marker for tumor-associated neutrophils." (PMID 38193534, 2024). "Polyamines also influence the immune microenvironment of solid tumors, particularly through the recruitment of immunosuppressive tumor-associated macrophages (TAMs), which express the enzyme arginase-1 involved in putrescine production, to CNS tumors." (PMID 39227460, 2024). "Because Arg1 is primarily expressed by cells of myeloid lineage in the TME, such as MDSCs and tumor-associated macrophages, we then focused on Arg1 positivity in individual CD11b+ cell subsets." (PMID 39195207, 2024). "Myeloid-derived suppressor cells (MDSCs), tumor-associated macrophages (TAMs), and neutrophils are the main sources of ARG1 in the TME." (PMID 39337272, 2024). "The M2 microglial phenotype has a characteristic arginase-1 (Arg1) activity, which is associated with the induction of tumor development via promoting cell proliferation, immune suppression, tissue remodeling, and angiogenesis." (PMID 39457052, 2024). "TAMs are often identified by CD11b and CD68, with markers such as IFN-γ and HLA-DR associated with an anti-tumor phenotype, while CD163, CD206, PD-L1 and ARG1 are associated with a tumor-promoting phenotype." (PMID 39310770, 2024). "Arg1 was selected because its expression is known to be significantly increased in neutrophils during tumor development, especially in tumor-associated neutrophils." (PMID 39595137, 2024). "Cytokines such as IL-4 and IL-13 within the tumor microenvironment regulate the polarization of tumor-associated macrophages (TAMs) through downstream Stat6-dependent inhibition of Arg1, activation of PPARγ, and TSC1-mediated inhibition of mTOR." (PMID 39676873, 2024). "Of the G-MDSCs that infiltrated the tumor, nearly all expressed Arginase-1, an indicator of their suppressive state that helps differentiate them from N1 tumor-associated neutrophils (TANs) that can have antitumor functionality." (PMID 37988164, 2024). "The tumor-promoting traits of TAMs are often linked to heightened Arg1 expression, which reduces nitric oxide levels and supports tumor growth." (PMID 38713256, 2024).
tumor (continued). "In contrast, IDC fibroblast-mediated tumor growth and invasion was associated with both tumor angiogenesis and recruitment of arginase-1+ cells." (PMID 37091166, 2023). "Arginase 1 activity is associated with the ability of MDSCs to inhibit cytotoxic T-cell activity due to the depletion of arginine, thus facilitating tumor immune escape." (PMID 37893077, 2023). "Here, we report that in HNSCC patients, high tumor Arg-1 protein expression was associated with favorable clinicopathological data and longer RFS, while high plasma levels of soluble Arg-1 were associated with unfavorable clinicopathological data." (PMID 38001706, 2023). "Our results demonstrate that Arg1 mRNA and ARG1 protein expression predominantly occurs in myeloid cells with Ly6G- and Ly6G+ intermediate expression associated with metastasis-able 66cl4 primary tumours." (PMID 37980483, 2023). "Previously, ARG1 expression has been linked to tumour-associated myeloid cells, independently of the metastatic potential of the tumour." (PMID 37980483, 2023). "Overexpression of arginase 1 (ARG1) and inducible nitric oxide synthase (iNOS) in myeloid-derived suppressor cells (MDSCs) and tumour-associated macrophages (TAMs) depletes both intracellular and extracellular arginine." (PMID 37144217, 2023). "HER2 and BP are fast-growing tumours that metastasize more readily than other tumour subtypes, suggesting an association between ARG1-positive cells and high grade and proliferation." (PMID 37980483, 2023). "Specifically, both KPmut-Late and KPloss-Late tumors exhibit significantly enriched immunosuppressive myeloid cells with high expression levels of Arg1 and Chil3, which resembles the phenotype of tumor-associated macrophage." (PMID 37998349, 2023). "The main source of ARG1 is myeloid cells, among which tumor-associated macrophages (TAMs) are an important source of ARG1." (PMID 38012650, 2023). "In line with this, Mafb/Maf editing induced a strong regulation of M1-associated genes (Inos, Ccl2, and Tnfa) and concomitant downregulation of M2-associated genes (Fizz1, Arg1, and Mrc2) in KCs of tumor-bearing mice." (PMID 36821387, 2023). "Targeting Arg1 in the acidic tumour microenvironment can cause decreased levels of tumour growth factors and can improve T effector functions leading to tumour regression." (PMID 36816957, 2023). "To determine how fibroblasts affected the microenvironment, we analyzed for changes in tumor angiogenesis and changes in arginase-1+ myeloid cells, cells that are typically associated with a pro-tumor response." (PMID 37091166, 2023). "Tumor escape from the host immune system has often been linked to the presence of immunosuppressive factors, such as Arg-1, in the TME." (PMID 38001706, 2023). "Most studies to date focused on Arg-1 released by myeloid cells, MDSCs or tumor-associated macrophages, while its role in cancer cells remains largely unclear." (PMID 38001706, 2023). "Tumor associated, TGFβ-dependent “N2” neutrophils bear ring-shaped nuclei and express relatively high levels of Arg1 and Vegf transcripts." (PMID 37961609, 2023). "At the same time, the edge is the proliferative area of the tumour, and ARG1-positive cells are associated with proliferation." (PMID 37980483, 2023). "In Ras-driven cancers, CXCL8 attracts tumour-associated neutrophils (TANs) to the tumour immune microenvironment, and TANs secrete arginase 1 to favour immune suppression." (PMID 37919768, 2023). "DCIS fibroblast-mediated tumor growth and invasion were associated with increased recruitment of arginase-1+ cells." (PMID 37091166, 2023). "Alpha-fetoprotein (AFP), alpha-L-fucosidase (AFU), arginase-1(Arg-1) are promising diagnostic tumor markers of HCC, and their measurements increased the detection sensitivity and specificity for HCC." (PMID 35081125, 2022). "Simultaneous expression of VEGF, IL-10, and arg-1 on tumor cells induces TIM-3 expression on BMDCs and tumor-associated DCs." (PMID 36713558, 2022).